MIR759 (microRNA 759)
Synonyms: hsa-mir-759
Gene: MicroRNA gene on chromosome 13 (52,810,050 to 52,810,140, forward strand). Ensembl gene ENSG00000211579.
Homologues: Orthologues: chimpanzee ptr-mir-759 (100% identical).